HIF1A (hypoxia inducible factor 1 subunit alpha)
Diseases named in the same sentence as HIF1A in open-access papers (continued):
Sharing a sentence is not in itself a finding about the gene and the disease.
ovarian carcinoma (continued). "A recent investigation demonstrated that the HIF-1α level is markedly enhanced in ovarian cancer in comparison with that in normal ovarian tissues and that the enhanced expression of HIF-1α is related to markedly shorter overall patient survival." (PMID 35464826, 2022). "miR-138 plays a tumor suppressive role in cancer biology by targeting many oncogenes, such as HIF‐1α in ovarian cancer." (PMID 35703312, 2022). "In ovarian cancer two important factors that participate in telomerase regulation (hTERT) are HIF-1α and c-Myc." (PMID 35974340, 2022). "HIF-1α also induces invasion and metastasis of ovarian cancer cells through the activation of the rate-limiting enzymes of the glycolysis pathway, hexokinase 2 and phosphofructokinase, to promote the Warburg effect." (PMID 36230617, 2022). "We further revealed HIF-1α expression and activation in ovarian cancer cells following LPS stimulation, which also involves the TLR-induced NF-κB activation." (PMID 35464826, 2022). "More importantly, we found that TRPM7 silencing promoted HIF-1α ubiquitination and degradation in ovarian cancer cells." (PMID 35101076, 2022). "2-ME, which has been approved by the FDA as an anti-cancer drug, is known to have anti-angiogenic effects and to target HIF-1α, and it is used to treat breast, prostate, and ovarian cancer in clinical trials." (PMID 35456989, 2022). "Hypoxia upregulated telomerase activity in ovarian cancer, colon cancer, cervical cancer, and renal cancer cell lines through transcriptional activation of hTERT by HIF-1α." (PMID 35681691, 2022). "The effect of AMPK activity on HIF-1α ubiquitination degradation was investigated in ovarian cancer cells." (PMID 35101076, 2022). "IL-6 can also induce HIF-1α activity via JAK/STAT signaling, which has been shown to be associated with chemoresistance to cisplatin in ovarian cancer." (PMID 36230617, 2022). "As it is a key regulator of glucose metabolism in ovarian cancer cells, activation of the PI3K/AKT/HIF-1α signaling pathway plays an important carcinogenic role in promoting the growth and metastasis of ovarian cancer." (PMID 35800058, 2022). "TRPM7 silencing enhanced AMPK activation to shift glycolysis to oxidative phosphorylation by promoting HIF-1α ubiquitination degradation in ovarian cancer." (PMID 35101076, 2022). "HIF-1α is inversely correlated with the expression of E-cadherin in ovarian cancer cell lines, SKOV3 and OVCAR3 as well as in vivo showing an attachment between hypoxia and metastasis." (PMID 36014432, 2022). "In vitro and in vivo, silencing TRPM7 increased the activation of AMPK and stimulated the ubiquitination and degradation of HIF-1α, thus attenuating the HIF-1α-enhanced glycolysis, and inhibiting the proliferation of ovarian cancer cells." (PMID 36844925, 2022). "Reportedly, the toll-like receptor 4 (TLR4)/nuclear factor kappa B (NF-κB) pathway and hypoxia-inducible factor-1α (HIF-1α) are activated and closely related to the chemoresistance and poor prognosis of epithelial ovarian cancer (EOC)." (PMID 35464826, 2022). "These two lines of evidence demonstrated that AMPK activation inhibited glycolysis that was dependent on high levels of HIF-1α presence in ovarian cancer." (PMID 35101076, 2022). "For instance, overexpression of HIF-1α induced by hypoxia increased autophagy in ovarian cancer cells, contributing to cisplatin resistance." (PMID 35931669, 2022). "Mechanistically, TRPM7 silencing significantly increased AMPK phosphorylation and decreased HIF-1α protein levels in ovarian cancer, particularly in HIF-1α silencing cells." (PMID 35101076, 2022). "Knockout of HIF-1α can redirect aerobic glycolysis in drug-resistant ovarian cancer cells to mitochondrial OXPHOS, resulting in cell death through the production of ROS, thus improving the response of cisplatin-resistant ovarian cancer cells to cisplatin." (PMID 35800058, 2022).
ovarian carcinoma (continued). "To further understand the importance of AMPK activation in shifting glycolysis to OXPHOS, we tested the effect of altered AMPK activation on the HIF-1α-regulated glycolysis in ovarian cancer cells." (PMID 35101076, 2022). "The majority of studies in ovarian cancer have indicated that elevated HIF-1α levels are a predictor of a poor prognosis." (PMID 36230617, 2022). "Mechanistically, TRPM7 silencing enhanced AMPK activation and promoted HIF-1α ubiquitination and degradation in ovarian cancer cells." (PMID 35101076, 2022). "In contrast, treatment with CC to inhibit AMPK activation minimized the shifting from glycolysis to OXPHOS, dependent on high HIF-1α levels in ovarian cancer cells." (PMID 35101076, 2022). "Together, TRPM7 silencing enhances the AMPK activation and decreases HIF-1α protein levels to shift glycolysis to OXPHOS in ovarian cancer cells." (PMID 35101076, 2022). "The current finding is not in line with our previous work in which showed that inhalational anesthetics had oncogenic effect via HIF-1a/miR-138 or -210 pathways in ovarian cancer (SKOV3) cells." (PMID 33919449, 2021). "Under hypoxic conditions, HIF-1α regulates increased STC2 expression to facilitate increased ovarian cancer tumor cell proliferation." (PMID 34867818, 2021). "In ovarian cancer, HIF-1α activates Notch1 signaling, which increases the activity of the Sox2 promoter, creating a CSC phenotype and drives drug resistance in ovarian cancer stem cells." (PMID 34867818, 2021). "In ovarian cancer cells, sulforaphane regulates the expression of HIF-1α and VEGF expression for inhibition of angiogenesis." (PMID 34094892, 2021). "Our research shows that the activation of HIF-1α or HIF-2α by cancer cells is related to the invasion ability of ovarian cancer cells." (PMID 34824343, 2021). "Had an inhibitory effect on the growth and migration of ovarian cancer cells by inhibiting the activation of mTOR and the induction of HIF1α." (PMID 35011278, 2021). "The schematic signaling pathway of LPA-induced DDR2 expression depicts the upregulation of DDR2 by LPA through coordinate activation of the PI3K/Akt/mTOR/HIF-1α signaling pathways and Twist1 expression to augment ovarian cancer cell invasion." (PMID 34065317, 2021). "Here, RNA pull-down results demonstrated that MIR210HG directly targets HIF-1α protein in ovarian cancer cells under hypoxic conditions." (PMID 34900667, 2021). "Collectively, the present study demonstrates that ATX, and thereby LPA, induces DDR2 expression through the activation of the PI3K/Akt/mTOR/HIF-1α/Twist1 signaling axes, aggravating ovarian cancer cell invasion." (PMID 34065317, 2021). "Increasing studies have found that in epithelial ovarian cancer, colorectal cancer, kidney cancer, liver cancer, salivary gland cancer, and other malignant tumors, HIF-1α induces VM by inducing EET." (PMID 33397409, 2021). "Specifically targeting HIF-1α through antisense as an anti-cancer strategy has shown efficacy in xenograft models of ovarian cancer." (PMID 34867818, 2021). "Increased levels of HIF1α promote the glucose uptake and lactate production of ovarian cancer cells." (PMID 33652661, 2021). "As HIF-1α drives cells toward anaerobic glycolysis, it supports the metabolic switch seen in ovarian cancer cells." (PMID 34867818, 2021). "Hypoxia is a common characteristic of many malignant tumors, and increased expression of hypoxia-inducible factor 1-alpha (HIF-1α) predicts the poor prognosis of ovarian cancer." (PMID 33435147, 2021). "Activation of the HIF-1α and Notch pathways in ovarian cancer can directly stimulate Sox-2 promoter activity." (PMID 33397409, 2021). "HIF-1α initiates autophagy in ovarian cancer cells exposed to hypoxia, and these cells develop resistance to cisplatin-induced apoptosis." (PMID 34867818, 2021). "It has also been reported that CDKN2B-AS1 interacts with miR-411-3p and regulates ovarian cancer progression via a HIF-1α/VEGF/p38 pathway." (PMID 34036383, 2021).
ovarian carcinoma (continued). "Increased levels of HIF1α promote the glucose uptake and lactate production in ovarian cancer cells." (PMID 33652661, 2021). "Here, we demonstrated that MIR210HG was induced by hypoxia, which is HIF-1α dependent and is mainly located in the cytosol of ovarian cancer cells." (PMID 34900667, 2021). "In an ovarian cancer model, HIF-1α suppressed miR-299 in the hypoxic cancer cells that were associated with the increased expression of heparanase HPSE1 and an elevated radioresistance." (PMID 33806538, 2021). "According to the earlier data, HIF1α regulates the expression of the ETS1 gene in PA1 ovarian cancer cells." (PMID 34136678, 2021). "Molecular investigations indicated that MIR210HG directly targets HIF-1α and inhibits VHL-dependent HIF-1α degradation in ovarian cancer." (PMID 34900667, 2021). "Knockdown of VHL also efficiently blocked shMIR210HG-mediated HIF-1α reduction in ovarian cancer cells, which suggested that MIR210HG regulates HIF-1α expression in a VHL-dependent manner." (PMID 34900667, 2021). "Our results indicated that MIR210HG was induced by hypoxia, which is HIF-1α dependent and mainly located in the cytosol of ovarian cancer cells." (PMID 34900667, 2021). "The mortality rate of ovarian cancer is increasing and the role of hypoxia inducible factor-1α (HIF-1α) in tumor progression has been confirmed." (PMID 34329303, 2021). "Culture of ovarian cancer cells under hypoxic conditions results in a concomitant increase in expression of HIF-1α and VEGF and inhibition of HIF-1α results in a significant decrease in VEGF production and tumor angiogenesis." (PMID 34867818, 2021). "Noteworthy, LPA was shown to activate HIF-1α via inducing a pseudohypoxic response, thus further modulating metabolism alterations in ovarian cancer mediated by HIF-1α." (PMID 34888248, 2021). "In colon and ovarian cancer cells, sulforaphane regulates the expression of HIF-1α and VEGF for inhibition of angiogenesis." (PMID 34094892, 2021). "Increases in HIF-1α and HIF-2α have both been suggested to be associated with ovarian carcinoma progression." (PMID 34692497, 2021). "Subsequent molecular studies suggested a possible crosstalk between AEG-1 and the HIF-1α/NF-κB/VEGF pathways indicating the role of AEG-1 as a promoter of ovarian cancer metastasis during hypoxic conditions, which was documented in a separate study." (PMID 33671513, 2021). "AKT/mTOR signaling pathway has been known to play a vital role in the manipulation of HIF-1α in ovarian cancer." (PMID 32312328, 2020). "The inhibitory effect of PAs on the expression of VEGF and hypoxia inducible factor 1 subunit alpha (HIF-1α) was also observed in cisplatin-resistant ovarian cancer cells." (PMID 33339407, 2020). "It is clear that HIF1-α coordinates with multiple resistance proteins in ovarian cancer, but more research should be done on the prevalence of hypoxia in ovarian solid tumors before assigning HIF1-α to biomarker status." (PMID 33182737, 2020). "Our data evidences a previously undescribed mechanism of DPP4 regulation in ovarian cancer cells mediated according to oxygen status, either directly via HIF-1α modulation or indirectly via its downstream targets." (PMID 33143089, 2020). "HE4 was found to activate STAT3 signaling and promote upregulation of the pro-angiogenic STAT3 target genes IL8 and HIF1A in immune cells, ovarian cancer cells, and endothelial cells." (PMID 32444701, 2020). "The expression of HVEM and HIF-1α under hypoxic conditions was higher than that under normoxic conditions, which suggested that the level of HVEM and HIF-1α correlates with prolonged periods of hypoxia in ovarian cancer." (PMID 32312328, 2020). "In this work, we explored the role of HVEM in hypoxic ovarian cancer cells and its effects on HIF-1α, a transcription factor responding to hypoxia." (PMID 32312328, 2020).
ovarian carcinoma (continued). "Recently, it has been demonstrated that AF inhibits HIF1α expression in an AhR-independent fashion in certain breast, renal and ovarian cancer cell lines." (PMID 32443455, 2020). "Correlates with increased HIF1α expression in patients with advanced stage ovarian cancer compared with patients with early-stage ovarian cancer." (PMID 32986358, 2020). "In this study, the expression of HVEM was found positively correlated to that of HIF-1α in ovarian cancer." (PMID 32312328, 2020). "Although upregulation of hypoxia response transcription factor HIF1-α is frequently observed in ovarian cancer, an established relationship between hypoxia and resistance to taxane chemotherapy has yet to be elucidated." (PMID 33182737, 2020). "Specific inhibition of HIF-1α with opium alkaloid noscapine sensitizes ovarian cancer (OC) cells to CDDP and downregulation of HIF-1α correlates with CDDP-induced apoptosis." (PMID 32235701, 2020). "Our previous findings have also confirmed that Nur77 can stabilize the expression of HIF-1α in hypoxic state of ovarian cancer cells (unpublished data)." (PMID 33245358, 2020). "Our findings are similar with the previous report describing that SU5416 inhibited VEGF and HIF-1α expression through the PI3K/AKT/p70S6K1 signaling pathway in ovarian cancer cells." (PMID 32432052, 2020). "A recent study demonstrated that adrenomedullin promoted tumor angiogenesis by up-regulating the level of VEGF and HIF-1α in ovarian cancer, which suggested the importance of HIF-1α in the treatment of ovarian cancer." (PMID 32312328, 2020). "It has been demonstrated that AKT/mTOR signaling pathway play a vital role in the regulation of HIF-1α in ovarian cancer." (PMID 32312328, 2020). "Both the high transduction efficiency and the increased mRNA and protein expression of HIF‐1α and HIF‐2α in HIF‐1A‐cDNA‐transduced and EPAS1‐cDNA‐transduced cells indicate that ovarian cancer cells successfully overexpressed either HIF‐1α or HIF‐2α." (PMID 30536571, 2019). "In order to validate this association, we monitored dynamic intracellular metabolic changes upon HIF-1A mRNA degradation (i.e., siRNA knockdown) in IGROV1 ovarian cancer cells, exhibiting an average basal level of HIF-1A activity." (PMID 31015463, 2019). "Ginsenoside Rg3 has been proved in ovarian cancer derived cells restraining HIF-1α expression by activating the ubiquitin-proteasome pathway." (PMID 31612116, 2019). "Previous studies have shown that HIF1A is activated in FSH-stimulated ovarian cancer cells SKOV-3, as well as in mouse granulosa cells where HIF1A was shown to be an inducible factor after FSH treatment in vivo and in vitro." (PMID 30811458, 2019). "SIRT1 is reportedly upregulated by HIF-1α and is involved in the promotion of cancer stem cell-like properties in ovarian cancer." (PMID 31068761, 2019). "In particular, LPA derived from ovarian cancer cells was recently shown to promote a glycolytic shift in ovarian cancer cells and in normal fibroblasts through HIF-1a, thus leading to the transformation of fibroblasts into cancer-associated-fibroblasts (CAFs)." (PMID 31652837, 2019). "In human ovarian cancer cells, HIF-1α promotes CSC-like properties by upregulating SIRT1 expression." (PMID 31428052, 2019). "In case of ovarian cancer 27 patients were those having high expression of HIF-1α, MDR1 and LAPTM4B while 10 patients were those having low expression of all the three genes, which showed a positive linear correlation among these genes (R = 0.849, p < 0.001)." (PMID 30746305, 2019). "Of note, GHET1 was found to interact with the E3 ubiquitin ligase von Hippel-Lindau (VHL), which consequently blocked VHL-mediated degradation of hypoxia-inducible factor-1α (HIF1α) and enhanced the protein level of HIF1α in ovarian cancer cells." (PMID 30988076, 2019).
ovarian carcinoma (continued). "Conversely, under hypoxic conditions, SIRT1 is a direct downstream target of hypoxia-inducible factor 1α (HIF-1α), which orchestrates with NF-κB pathway to promote cancer stem cell-like properties in ovarian cancer cells." (PMID 31068761, 2019). "HIF-1α expression represents an important biomarker in the evaluation of ovarian carcinoma prognosis." (PMID 30678691, 2019). "In the present study, we identified GHET1 as a novel binding partner of VHL, which consequently promoted the protein stability of HIF1α and enhanced the glucose metabolism of ovarian cancer cells." (PMID 30988076, 2019). "In another study, it was found that ovarian cancer cells exogenously expressing HCG induced an overexpression of HIF-1α." (PMID 31612116, 2019). "Ovarian cancer includes high expression levels of human chorionic gonadotropin and HIF-1α, which contribute to cell proliferation and tumor growth." (PMID 31993365, 2019). "The molecular study uncovered that GHET1 interacted with VHL and blocked the binding between VHL and HIF1α, which led to the stabilization of HIF1α and up-regulation of glycolysis of ovarian cancer cells." (PMID 30988076, 2019). "Overexpression of GHET1 promoted the glycolysis of ovarian cancer cells via modulating VHL-mediated degradation of HIF1α." (PMID 30988076, 2019). "We found that CT inhibited glucose metabolism in ovarian cancer cells through inducing SIRT3/HIF‐1α signaling pathway." (PMID 30094960, 2018). "The obtained results suggest that dysregulation of O-GlcNAcylation, and the related HIF1A pathway, via hyperglycemia, is responsible for the decreased cytotoxic efficiency of metformin in human ovarian cancer cells." (PMID 30217067, 2018). "One of them is the HIF1A pathway that is launched by the hyperactive mTOR pathway in different cancer cells, including ovarian cancer." (PMID 30217067, 2018). "In summary, the present study investigated the cross-talk between the VEGF/VEGFR/HIF-1α system and melatonin therapy in an ethanol-preferring rat model of ovarian carcinoma." (PMID 28398226, 2017). "The results above demonstrated that there was a significant correlation between HIF-1α expression and CSCs-like features in ovarian cancer." (PMID 28878214, 2017). "Our present studies have found that the high expression of HIF-1α promoted CSCs-like features in ovarian cancer cells, including CSCs’ markers expression, chemoresistance, tumorigenesis and EMT phenotype." (PMID 28878214, 2017). "A clinically validated HIF1α-inhibitor (PX-478) was very recently tested in vitro and successfully inhibited the invasion/migration process of ovarian cancer cells." (PMID 28402936, 2017). "The functional significance of this interaction was investigated by assessing the effect of HIF‐1α knockdown on invasive phenomenon of ovarian cancer cells." (PMID 28236660, 2017). "Our data indicated that HIF-1α contributed to the malignance of ovarian cancer for promoting CSC-like characteristics." (PMID 28878214, 2017). "In summary, our studies showed a novel pathway of HIF‐1α associated AEG‐1 induction, which is a protein that mediates the migration and invasion of ovarian cancer cells." (PMID 28401704, 2017). "Collectively, it can be suggested that transcriptional induction of ETS‐1 is directly regulated by HIF‐1α in ovarian cancer cells." (PMID 28236660, 2017). "Hypoxia is a common characteristic of many malignant tumors, and increased HIF-1α expression predicts the poor prognosis of ovarian cancer." (PMID 28878214, 2017). "When treated with LPA, ovarian cancer cells multiplied by 150 the HIF1α secretion in vitro, through the Gαi2 protein secretion (a protein activated by the LPAR)." (PMID 28402936, 2017). "In our work, we found that SIRT1 was overexpressed in ovarian cancer cells exposure to hypoxia condition, and its expression was regulated by HIF-1α." (PMID 28878214, 2017).